CD59 (CD59 molecule (CD59 blood group))
Diseases named in the same sentence as CD59 in open-access papers (continued):
Sharing a sentence is not in itself a finding about the gene and the disease.
cancer (continued). "Taken together the findings are consistent with the conclusion that future immunotherapies should aim to achieve a highly specific and profound activation and deposition of complement as well as to disrupt the synthesis and expression of CD59 and CD55 by the cancer cells." (PMID 17623109, 2007). "Additionally, TGFβ-dominant cancers such as CESC, GBM, HNSC, and STAD may use CD59 as an immune escape mechanism by blocking MAC formation and increasing the population of Treg, MDSC, and TAM." (PMID 39518137, 2024). "CD59 has several additional functions relevant to immune function, including the complement activation cascade where it binds to C8 and C9 to inhibit the formation of membrane attack complex (MAC) pores, conferring cancer cells resistant to complement-mediated cell lysis." (PMID 39436703, 2024). "However, to date no studies on the pathobiological role of CD59 in EVs or its potential clinical utility in cancer detection has been reported." (PMID 36612172, 2022). "Whether CD55 and/or CD59 play a role in protecting cancer cells from mAb-mediated CDC in vivo is not completely clear." (PMID 33126570, 2020). "Interestingly, the expression of CD46, CD55, and CD59 was suppressed in U2-OS cells compared with human endothelial cells or other cancer cells which did not activate the complement system." (PMID 29615744, 2018). "The reason for the low levels of CD59 in the urine of cancer patients is not understood." (PMID 21083881, 2010). "Our analysis reveals that the negative correlation between CD59 and Treg contributes to a less immune suppressive TME in KIRC, unlike the positive correlation in CESC, GBM, HNSC, and STAD cancers." (PMID 39518137, 2024).
infection (22 papers, 2009 to 2025). The state of being infected such as from the introduction of a foreign agent such as serum, vaccine, antigenic substance or organism. "Hence, it seems that the hemolytic anemia caused by infection with E. Coli O104:H4 is being counteracted by a lasting elevation of CD59 on erythrocytes considering the mean erythrocyte life time of 120 days and the 3 month long time period since patients’ discharge." (PMID 24086391, 2013). "Infection of the donor AAV alone also restored the surface expression of CD59 in PIGO-KO HEK293 cells, suggesting the weak ITR-driven expression of the full-length Pigo cDNA." (PMID 35661110, 2022). "In sharp contrast, the frequency of coincidence of CD147 with EEA1 increased over time during infection similarly to the CD59 results." (PMID 30042195, 2018). "In this study, we found that CD59 was upregulated by infection of A549 cells with PIV5-based viruses including PIV5 WT and the PIV5 Le-(U5C, A14G) mutant as well as by RSV infection." (PMID 29693588, 2018). "We used flow cytometry analysis to quantify the cell-surface levels of CD55, CD46, and CD59 during infection." (PMID 30190327, 2018). "Viruses such as human herpesvirus 7 have been shown to induce CD59 expression during infection of target cells." (PMID 29693588, 2018). "At 2 dpi, CD59 mRNA was induced by PIV5 infection ~3 fold compared to mock infected cells and there was a ~6 fold increase in cell surface CD59 expression." (PMID 29693588, 2018). "Infection with PIV5 as well as other RNA viruses results in increased levels of CD59 on the cell surface." (PMID 29693588, 2018). "These CD59-knock down (KD) cells were infected with HCVJc1 and the supernatant was harvested 48 h post infection." (PMID 23049856, 2012). "Consistent with earlier work, regulators of complement activation, CD46, CD55 and CD59, were slightly enhanced after VV and VV:ΔHA infection (unpublished results)." (PMID 21901096, 2011). "As was mentioned, CD59 is heavily down-regulated at the 3 hpi infection time point in the resistant family; therefore CD59–C8a interaction may play an important role in the NNV infection of sea bass, and needs further study." (PMID 41009783, 2025). "In patients with a high proportion of type II cells, the partial expression of CD59 may protect from the majority of spontaneous haemolysis, with haemolysis mainly occurring during periods of enhanced complement activation, such as infection or trauma." (PMID 39201278, 2024). "Cd59 is best known for its ability to inhibit complement-dependent cell lysis, protecting healthy cells from premature death during times of inflammation, such as during an infection or after an injury." (PMID 35748863, 2022). "In response to ONNV MOI 1, SC reduced CD55 and CD59 gene expression by about two-fold (2.89 × 10−3 ± 1.41 × 10−3, p < 0.05) and three-fold (1.19 × 10−2 ± 3.31 × 10−3, p < 0.05), respectively, at 24 h post infection." (PMID 36611893, 2022). "Similarly, infection of H1299 WT host cells with a ΔLecA PAO1 mutant strain reduced the invasion efficiency to comparable levels of WT PAO1 invasion into CD59- or flotillin-depleted cells." (PMID 33555391, 2021). "Interestingly, infection of Cd59-/- mice and analysis of CDC in WT and Daf-/- primary lung cells indicated that the last step of the complement cascade does not impact disease outcome in IAV infection." (PMID 34197564, 2021). "CD59 was revealed to be a general infection marker in monocytes." (PMID 29899248, 2018). "These correlations suggest that specific viral gene products such as the viral glycoproteins or dsRNA generated during an infection might be strong inducers of CD59 pathways." (PMID 29693588, 2018). "Indeed, CD55 and CD59 expression were generally higher in subjects who recuperated from an infection with E. Coli O104:H4 than in HC." (PMID 24086391, 2013). "Interestingly, antibodies against CD59 block infection to a range of echoviruses in RD cells." (PMID 31739586, 2019).
infection (continued). "We sought to understand how CIE was altered by infection since CIE governs the trafficking of proteins known to be affected by HCMV and by a number of immune regulators, such as MHC-I and CD59." (PMID 30042195, 2018). "As the reporter cells were not affected, when we applied the same experimental conditions as in the neutralization/infection assay, we concluded that the reduced infectivity of HCV in the presence of NHS and anti-CD59 Abs is related to CML of the virus." (PMID 23049856, 2012). "Several regulators of the complement system, including complement factor H, complement factor I, and CD59, are downregulated by SARS-CoV-2, which may contribute to complement dysregulation during infection." (PMID 39040605, 2024). "Infection of A549 cells with PIV5 and RSV upregulated CD59 expression." (PMID 29693588, 2018). "By contrast, there was no increased CD59 expression following infection with PIV2, Zika virus, and MuV." (PMID 29693588, 2018). "Our data do not support a role for CD55 and CD59 in HUS development during EAHEC O104:H4 infection and point to a different mechanism within the complement system for HUS development in EAHEC patients." (PMID 24086391, 2013). "The presence of CD59 from mock-transfected and reduction/absence of CD59 of siCD59 treated as well as the infection of the cells were assessed by Western blot analysis." (PMID 23049856, 2012). "The prominent expression of the membrane-anchored RCAs prompted us to test, whether in the experimental setting used for the lysis/infection assay of Huh7.5 cells with HCV, the reporter cells are still attacked and lysed by the complement system in the presence of anti-CD59." (PMID 23049856, 2012). "Similar observations were seen in hepatocytes infected with HBV and this downregulation was specific to CD59, as neither CD55 nor crry (another complement controlling protein) were significantly changed upon infection." (PMID 31739586, 2019). "Interestingly, infection of CD59- or flotillin-depleted cells with ΔLecA PAO1 did not further lower the invasiveness, which suggests that LecA, CD59 and flotillins act in the same pathway." (PMID 33555391, 2021).
cardiovascular disease (4 papers, 2016 to 2025). "In line with our theory of CD59 shedding from endothelial cells after hemodynamic stress, PD-induced vasculopathy could also explain its association with future loss of RRF as a common pathway of cardiovascular disease and interplay to produce these outcomes." (PMID 33306183, 2021). "Chronically increased internalization of endothelial CD59, which appears to occur in untreated OSA before the onset of clinically evident cardiovascular disease, may underlie chronic endothelial inflammation that likely contributes to the well-documented increased cardiovascular risk in OSA." (PMID 26738794, 2016). "Statins, commonly used to treat cardiovascular diseases, have previously been shown to upregulate CD55 and CD59 expression in human umbilical vein endothelial cells." (PMID 37357314, 2023).
bacterial infections (3 papers, 2016 to 2025). "Among these genes, certain genes involved in the complement cascade were expressed at lower levels in the resistant family (c2, c6, cr1 or cd59), in contrast to what was found in head kidney samples after bacterial infection." (PMID 39712009, 2024).
peripheral neuropathy (1 paper, 2023). A disorder affecting the peripheral nervous system. "Homozygous CD59-deficient patients manifest with recurrent peripheral neuropathy resembling Guillain-Barré syndrome (GBS), hemolytic anemia and recurrent strokes." (PMID 37875972, 2023).
renal diseases (1 paper, 2016). "CD59 and decay accelerating factor (DAF) are synthesized by mesangial and epithelial cells, and complement activation translates into higher levels of both in a number of renal diseases, among them those with glomerular injury." (PMID 26772976, 2016).
CD59 also shares sentences with these, for which no sentence is quoted: Gestational Diabetes Mellitus (5 papers); pancreatic ductal adenocarcinoma (3); asthma (2); autoimmune disease (2); autoimmune thrombocytopenia (2); choroidal neovascularization (2); diffuse large B-cell lymphoma (2); insulin-dependent diabetes (2); lung adenocarcinoma (2); neurodegenerative disease (2); retinal degeneration (2); systemic lupus erythematosus (2); abortion (1); acute myeloblastic leukemia (1); acute promyelocytic leukemia (1); acute respiratory distress syndrome (1); angioedema (1); antiphospholipid syndrome (1); atypical hemolytic-uremic syndrome (1); benign prostatic hyperplasia (1); bone marrow disease (1); brain injury (1); breast adenocarcinoma (1); bronchiolitis obliterans syndrome (1); bullous pemphigoid (1); cardiac disease (1); cardiac ischemia (1); cardioembolic stroke (1); cerebral malaria (1); cervical squamous cell carcinoma (1).
A further 54 diseases each share a sentence with CD59 in 1 paper.